CCR7 (C-C motif chemokine receptor 7)
Diseases named in the same sentence as CCR7 in open-access papers (continued):
Sharing a sentence is not in itself a finding about the gene and the disease.
non-Hodgkin lymphoma (3 papers, 2011 to 2025). Distinct from Hodgkin lymphoma both morphologically and biologically, non-Hodgkin lymphoma (NHL) is characterized by the absence of Reed-Sternberg cells, can occur at any age, and usually presents as a localized or generalized lymphadenopathy associated with fever and weight loss. "CCR7-enhanced migratory ability is, at least in part, due to EMT characteristics that were observed in several cancers including breast, bladder, bone, colorectal, gastric, head and neck, lung, pancreatic, prostate, thyroid, B-CLL and non-Hodgkin’s lymphoma." (PMID 35203305, 2022). "No such studies have been done on CCR7 expression in non-Hodgkin's lymphoma (T-NHL)." (PMID 21548969, 2011).
osteoarthritis (3 papers, 2014 to 2023). A noninflammatory degenerative joint disease occurring chiefly in older persons, characterized by degeneration of the articular cartilage, hypertrophy of bone at the margins and changes in the synovial membrane. "For example, synovial fluid T cells from rheumatoid patients showed enhanced CCR7- and high Kv1.3 expression, whereas T cells from osteoarthritis patients were CCR7+ with low Kv1.3 expression." (PMID 37705981, 2023). "CCL21 and CCR7 are expressed in chronic articular inflammatory diseases such as osteoarthritis and rheumatoid arthritis." (PMID 30914733, 2019). "The expression levels of CCL19, CCL21 and their receptor CCR7 in AS (n = 31) and osteoarthritis (OA, n = 21) LT were analyzed via real-time polymerase chain reaction (RT-PCR) and immunohistochemistry (IHC)." (PMID 25260647, 2014).
pancreatic ductal adenocarcinoma (3 papers, 2013 to 2022). An infiltrating adenocarcinoma that arises from the epithelial cells of the pancreas. "The aim of the present study was to investigate the association between the expression of chemokine receptors CCR7 and CXCR4 and vascular endothelial growth factor (VEGF)-C and the lymph node metastasis of pancreatic ductal adenocarcinoma (PDAC)." (PMID 23761820, 2013).
pneumonia (3 papers, 2021 to 2023). An acute, acute and chronic, or chronic inflammation focally or diffusely affecting the lung parenchyma, caused by an infection in one or both of the lungs (by bacteria, viruses, fungi, or mycoplasma.). "Collectively, these results identify monocyte CCR7 as a potentially important player in the host response during pneumonia." (PMID 38077404, 2023). "We found the exhaustion of CD4+ TEM in patients with acute pneumonia accompanied with a decrease of CCR7+CD45RA+ naïve T cells (CD38+HLA‐DR+)." (PMID 34841705, 2021). "The expression of G protein‐coupled receptor (GPR) 183 and CCR7 was positive on CD8+ T cells in acute pneumonia." (PMID 34841705, 2021). "CCR7 in cluster 09 increased significantly only in peripheral CD3+ T cells of the patients with acute pneumonia." (PMID 34841705, 2021). "Nevertheless, several of them, SELL, GZMB, and CCR7 (at 3 dpi), and HAVCR2 (TIM-3), TNFRSF9 (CD137), and GPR18 (at 6 dpi) were promptly upregulated for the virulent Lena strain, probably associated with the marked clinical signs, the earlier and stronger peak of replication, and severe pneumonia." (PMID 34851149, 2022). "The expression levels of CD59, CD28, CCR7, CD270, Tim3, Eomes, lymphocyte activation gene‐3 (LAG3), TCRab and TIGIT were higher, while that of OX40, CD45RO, PD‐L1 and CD25 lower in cluster 09 in patients with acute pneumonia." (PMID 34841705, 2021).
prostate tumor (3 papers, 2019 to 2021). "Within the global CD45+ immune cell population, CCR7+ population correlated with smaller prostate tumor volume (PTV) (r = − 0.507, p = 0.026) and less extra-prostatic extension (EPE) (r = − 0.517, p = 0.023)." (PMID 34588590, 2021). "Another prior study has shown that TNF-α directly and/or indirectly induces proteases such as MT1-MMP and MMP9, and also promotes CCR7 upregulation, thereby contributing to cancer cell migration from breast and prostate tumors." (PMID 33816268, 2021). "His study verifies that silencing of CCL19 reduces tumor cell proliferation and suppresses invasion and migration, suggesting that the CCL19/CCR7 axis may mediate the pathogenesis of human prostate tumor." (PMID 30430424, 2019).
pulmonary disease (3 papers, 2014 to 2022). "In fact, respiratory syncytial virus infection may accelerate pulmonary disease via CCR7-related mechanisms." (PMID 24507453, 2014). "It was found that smoking may correlate with elevated CCR7 mRNA expression level, that CCR7 plays a major role in modulating inflammatory responses in airways in pulmonary diseases, and that cigarette smoking upregulates CCR7, CCL19, and CCL21 mRNA expression levels in lymph nodes of wild-type mice." (PMID 35160116, 2022). "Using the expressions of PD‐1, chemokine C–C motif receptor 7 (CCR7), CD45RA, CD38 and HLA‐DR, we analyzed proportion of exhausted and activated CD4+ and CD8+ T cells in healthy volunteers and patients with lung diseases, respectively." (PMID 34841705, 2021).
Salmonella Infections (3 papers, 2011 to 2023). Infections with bacteria of the genus SALMONELLA. "Prior studies have reported similar findings that augmenting inflammation in the gastrointestinal tract (e.g. Rnf5−/− mice or Salmonella infection) increases DC mobilization into MLNs and TDLNs in a CCR7-dependent manner." (PMID 36867675, 2023). "In mouse peritoneal MΦs, Salmonella infection up-regulated the expression of both of M1 MΦ markers (CCR7 and CD86), M2 MΦ marker (CD163 and CD206) and induced the secretion of M1 MΦ marker TNF-α and M2 MΦ marker IL-10 in ascitic fluid significantly." (PMID 30271755, 2018).
sarcoma (3 papers, 2021 to 2024). A usually aggressive malignant neoplasm of the soft tissue or bone. "SQLE expression was negatively correlated with the expression of chemokines (CCL19 and CX3CL1) and chemokine receptors (CCR2 and CCR7) in sarcoma." (PMID 38335381, 2024). "Both CD83 and CCR7 upregulation was significant also when compared to DCs loaded with untreated sarcoma cells." (PMID 33717062, 2021).
SARS-CoV infection (3 papers, 2014 to 2021). "Most were upregulated such as PTGES, MIF, CCR7, CXCL6 and CXCL12, which encodes immune cytokines known to be transcriptionally upregulated during SARS-CoV infection." (PMID 34282405, 2021). "Although no age-dependent differences were observed in the frequency of naïve (CD45RA + CCR7+) CD8 T cells in peripheral blood, there were significantly lower levels of these cells in the lung and lymph node of aged animals during SARS-CoV infection (unpaired student T-tests)." (PMID 24642138, 2014).
steatosis (3 papers, 2016 to 2023). Increased lipid within the cytoplasm of cells. "Alteration in CCR7, IMPDH2, IL6ST, MYC, LPIN1, PDE7A and RORA was significantly associated with hepatotoxicity including liver damage, -hyperplasia, -inflammation, -steatosis, -fibrosis, -necrosis and -proliferation." (PMID 26907258, 2016).
AIDS (2 papers, 2010 to 2022). A syndrome resulting from the acquired deficiency of cellular immunity caused by the human immunodeficiency virus (HIV). "Chemokine receptors, such as CXCR3, CXCR4, CCR5, and CCR7, play a critical role in many infectious diseases, including AIDS and TB." (PMID 35712309, 2022). "However, by 12 weeks post infection differences in mDC activation were evident between groups particularly with respect to the chemokine receptor CCR7, which was expressed by a significantly greater proportion of mDC in animals that progressed to AIDS relative to animals with stable infection." (PMID 21203477, 2010).
aneurysm (2 papers, 2021 to 2022). Bulging or ballooning in an area of an artery secondary to arterial wall weakening. "Results showed CCR7, TNF and CXCR4 related miRNA-genes network were preserved in all three kinds of aneurysms, which highlighted the common molecular networks shared by aneurysmal diseases." (PMID 34637689, 2021).
B-cell Acute Lymphocytic Leukemia (2 papers, 2010 to 2022). "In childhood B-cell lymphoblastic leukemia cells, pre-B cells expressed CCR7 and migrated to CCL19, suggesting that CCR7 plays an important role in pre-B-cell lymphoblastic leukemia chemotaxis, whereas pro-B cells required the presence of the CD40 ligand to be CCL19/CCR7 responsive." (PMID 35203305, 2022).
bronchiolitis obliterans syndrome (2 papers, 2010 to 2016). A lung disorder that is mainly associated with chronic allograft dysfunction after lung transplantation and that is characterized by inflammation and fibrosis of bronchiolar walls that reduce the diameter of the bronchioles and result in progressive and irreversible airflow obstruction. "Elevated levels of CXCR4 and CCR7 in respiratory epithelial lining fluid has been reported in patients with obliterative bronchiolitis (OB) after lung transplantation (LTP)." (PMID 27309347, 2016).
carotid atherosclerosis (2 papers, 2021 to 2023). A thickening and loss of elasticity of the walls of carotid arteries that occur with formation of atherosclerotic plaques. "We discovered that CCL21 was downregulated, and that its receptor, CCR7, was upregulated in preeclamptic placentae, which was consistent with the findings of carotid atherosclerosis." (PMID 36829431, 2023). "The current findings suggest that CCR7 is immunohistochemically localized to macrophages and vascular SMCs via carotid atherosclerosis and highlight that although CLL19 and CCL21 are signaling through CCR7, they may have different effects on macrophages and SMC." (PMID 34777635, 2021).
cervical squamous cell carcinoma (2 papers, 2021). A squamous cell carcinoma arising from the cervical epithelium. "The unique CD45RA +/CCR7 + phenotype of HPV antigen-induced T cells can serve as a specific marker for dysfunctional T cells in HPV16-induced squamous cell cervical cancer." (PMID 34833360, 2021).
Chagas disease (2 papers, 2017 to 2018). A parasitic infection caused by Trypanosoma cruzi. "Some of these differentially expressed genes were previously associated to Chagas disease (eg, IL7, CCR7, CCL19, GATA4, HLA-DPB1)." (PMID 28575239, 2017).
chordoma (2 papers, 2023 to 2025). Chordomas are rare malignant tumors arising from embryonic remnants of the notochord in axial skeleton. "The correlation of CCR7 and other core T cell-associated genes with CD4+ and CD8+ T cell infiltration further supports their functional relevance in the chordoma immune microenvironment." (PMID 40386066, 2025). "The convergence of network analysis and machine learning on CCR7 as a central immune regulator in chordoma is particularly intriguing." (PMID 40386066, 2025). "Consensus clustering identified a highly immunogenic chordoma subtype (Cluster 1), and WGCNA and machine learning converged on CCR7 as a central immune regulator, with core T cell-associated genes correlating with immune cell distribution patterns." (PMID 40386066, 2025). "This study reveals a complex immune microenvironment in chordoma, characterized by elevated immune checkpoint expression (e.g., PD-1, CTLA-4), a highly immunogenic subtype (Cluster 1), and a T cell-centric regulatory network with CCR7 as a key modulator." (PMID 40386066, 2025). "Additionally, CD4 T‐cell clusters had widespread overexpression of naïve markers (CCR7, SELL, LEF1 and TCF7), suggesting that CD4 T cells were in a naïve state in chordoma." (PMID 37784253, 2023).
chronic hepatitis C (2 papers, 2017 to 2023). "One study reported that CCL21 expression during chronic hepatitis C is implicated in the recruitment of T lymphocytes and may promote fibrogenesis via the activation of CCR7 on hepatic stellate cells (HSCs)." (PMID 37296834, 2023). "Expression of CCL21 was also involved in the organization of inflammatory lymphoid tissue and the recruitment of T-cells, which may promote fibrogenesis via activation of chemokine receptor 7 (CCR7) on HSCs during chronic hepatitis C." (PMID 29137226, 2017).
Cognitive impairment (2 papers, 2023 to 2024). Abnormal cognition is characterized by deficits in thinking, reasoning, or remembering. "The cognitive impairment in CCR7–/– mice was accompanied by an aberrant accumulation of CD4 and CD8 T cells in the dura and, conversely, a steep decrease in T cell content in the cervical LNs." (PMID 37580702, 2023). "Indeed, dural T cells in aged mice have reduced expression of CCR7, an important receptor necessary for mediating the lymphatic drainage of these cells, and deletion of Ccr7 leads to neurovascular and cognitive impairment [98•]." (PMID 38613621, 2024). "Interestingly, loss of hematopoietic CCR7 in adult mice was enough to recapitulate the increased numbers of both effector (IFN-γ-producing) and Tregs in the dura that is seen in old mice, as well as the reduction in glymphatic influx of CSF and an early appearance of cognitive deficits." (PMID 37580702, 2023).
colorectal tumor (2 papers, 2015 to 2023). "Further bioinformatic analyses revealed that several immune cell markers, including CCR7, CD40LG, and CD3G, were among the most positively correlated genes with DNASE1L3 in human colorectal tumors, indicative of a possible association between DNASE1L3 expression and antitumor immune activity." (PMID 37581941, 2023). "We have previously shown that the SNs of colorectal tumor cells that had been treated with RT plus HT also induce a significant up-regulation of expression of CD80 and CCR7 on DCs and that Hsp70 is one mediator of it." (PMID 26383236, 2015).
cutaneous leishmaniasis (2 papers, 2013 to 2024). Leishmaniasis affecting the skin. "Therefore, we decided to test the role of CCR7 in a gene-deficient model during experimental cutaneous leishmaniasis." (PMID 24205367, 2013). "While cutaneous leishmaniasis has been studied in a model with transgenically decreased CCR7 expression, toxoplasmosis is the only parasitic model investigated to date in the CCR7-/- mouse model, and this model shows a high degree of susceptibility." (PMID 24205367, 2013). "Disruption of the normal function and migration of these cells in the absence of CCR7 during cutaneous leishmaniasis causes a chronic infection." (PMID 24205367, 2013). "Additionally, the absence of CCR7 in monocytes disrupts migration and facilitates immunosuppression, leading to conditions such as chronic cutaneous leishmaniasis." (PMID 38742110, 2024).
dermatitis (2 papers, 2016 to 2021). An inflammatory process affecting the skin. "Variants at ARRCD1 and CCR7/SMARCE1 were previously identified in a study on the broader phenotype “dermatitis or eczema” in UKBB18." (PMID 34785669, 2021). "Wild-type (WT) and Ccr7−/− mice showed similar levels of skin inflammation in the IL-23 injected ears, suggesting that homing of tDCs into the skin-draining lymph nodes is not critical for the IL-23-induced skin inflammation." (PMID 27982014, 2016).
eosinophilia (2 papers, 2018 to 2021). "Consistent with the higher percentage of CCR4+CD45RA−CD45RO+CCR7+ CD4+ T cells in patients without blood eosinophilia, atopic asthma patients without blood eosinophilia showed an increase of CRTH2+CD45RA−CD45RO+CCR7+ CD4+ T cells, compared to control subjects." (PMID 29507584, 2018).
Ewing sarcoma (2 papers, 2016 to 2022). A small round cell tumor that lacks morphologic, immunohistochemical, and electron microscopic evidence of neuroectodermal differentiation. "Only one of twenty-four Ewing sarcoma patient tissues was positive for CCR7 or CCL21." (PMID 35203305, 2022). "Protein expression analysis of CCL21 and its receptor CCR7 in 24 therapy-naïve tumors showed that there was no expression in all bar one Ewing sarcoma cells." (PMID 27369431, 2016).
experimental autoimmune encephalomyelitis (2 papers, 2023 to 2026). An autoimmune demyelinating disease of the central nervous system that is produced experimentally in animals by the injection of homogenized brain or spinal cord in Freund's adjuvant. "Furthermore, in experimental autoimmune encephalomyelitis models, CCR7 signaling is involved in immune cell recruitment and the regulation of Th1/Th17 responses." (PMID 41481752, 2026).
Granuloma (2 papers, 2015 to 2022). A compact, organized collection of mature mononuclear phagocytes, which may be but is not necessarily accompanied by accessory features such as necrosis. "The most abundant subcluster (8.3% of granuloma cells, q = 0.074, Dirichlet p = 0.00049) exhibited elevated expression of markers of naive and memory T cells (TCF7, CCR7, IL7R, and TXNIP) and activation or memory state (CD69 and ITGB1)." (PMID 35483355, 2022). "The expression levels of CXCL10, CXCL11, CCR7, CCL17 and CCL18 in the tuberculous granuloma were measured by quantitative real-time RT-PCR and were compared with the levels detected in lung tissues without granulomas." (PMID 26091535, 2015).
helminth infection (2 papers, 2015 to 2017). "Finally, using a helminth infection model we show that accumulation of LTi-like ILC3s in the draining LN requires CCR7 expression." (PMID 25575242, 2015). "It is possible that at later stages of immune activation during helminth infection, CXCR5 becomes more important for T cell polarization and for T follicular helper cell differentiation, while in the early stages of Th2 induction CCR7 plays a more dominant role." (PMID 28716804, 2017).
Hodgkins lymphoma (2 papers, 2016 to 2022). A heterogeneous group of malignant lymphoid neoplasms of B-cell origin characterized histologically by the presence of Hodgkin and Reed-Sternberg (HRS) cells in the vast majority of cases. "Hodgkin’s lymphoma migrated to the interfollicular zone of lymph nodes and expressed CCR7, which was dependent on NF-kB." (PMID 35203305, 2022).
Hypertension (2 papers, 2012 to 2020). The presence of chronic increased pressure in the systemic arterial system. "For example, the target genes CCR7 and CD247 were shown to be involved in the regulation of immune inflammatory cell function, contributing to end organ damage in hypertension." (PMID 32338289, 2020).
idiopathic interstitial pneumonia (2 papers, 2011 to 2024). A class of diffuse lung diseases that typically affect the pulmonary interstitium, although some also have a component affecting the airways (for instance, Cryptogenic organizing pneumonitis). "CCR7 expression was significantly raised in different forms of idiopathic interstitial pneumonias, suggesting that CCR7 positive cells are activated resident pulmonary fibroblasts." (PMID 22205929, 2011). "In lung samples of idiopathic interstitial pneumonia, CCL19 is elevated, and CCR7 protein was expressed in interstitial areas restricted to blood vessels and mononuclear cells." (PMID 39768150, 2024).
kidney failure (2 papers, 2016 to 2022). An acute or chronic condition that is characterized by the inability of the kidneys to adequately filter the blood. "Additionally, kidney failure comes along with a thymus involution and thus reduced distribution of CCR7+ RTEs." (PMID 35592311, 2022).
leishmaniasis (2 papers, 2013 to 2021). Infectious disease that is transmitted through the bite of hematophagous female phlebotomine sand flies. "In “other diseases” (such as leishmaniasis), a higher count of CCR7+ naïve T cells was also reported, compared with those of the normal groups 41, indicating greater proliferative potential in these diseases." (PMID 33391397, 2021). "We sought to determine the effects of the absence of CCR7 on the resolution of leishmaniasis, as well as the composition and function of the inflammatory infiltrate." (PMID 24205367, 2013).
Listeria infection (2 papers, 2013 to 2019). "The western blotting results verified this polarization tendency; CCR7 expression was significantly higher after Listeria infection than in the control group, while the results of the expression of the M2 marker Arg-1 was opposite." (PMID 31133815, 2019).